GATA6 (GATA binding protein 6)
Diseases named in the same sentence as GATA6 in open-access papers (continued):
Sharing a sentence is not in itself a finding about the gene and the disease.
tumor (continued). "Immunohistochemical staining revealed a significant reduction in Ki67-positive cells in tumors derived from GATA6- or TET1-depleted CAFs (P < 0.01 vs. control), indicating suppressed tumor cell proliferation." (PMID 40216762, 2025). "Overall, our findings demonstrate that GATA6 and TET1 are critical regulators of CAF identity, survival, and tumor-promoting functions." (PMID 40216762, 2025). "The concordance at the protein level was verified by performing dual IHC (GATA6/S100A2) in one case with differential expression and two cases with equivalent RNA expression between the primary tumor and the liver metastasis." (PMID 39935174, 2025). "It was observed that GATA6 hindered EMT and decreased cell spreading, indicating a role in suppressing tumor growth." (PMID 40699746, 2025). "When p300 was lost, GATA6 levels dropped, triggering a shift from the PDAC subtype to an aggressive basal-like/squamous subtype, increasing tumor aggressiveness and reducing differentiation." (PMID 40699746, 2025). "It was revealed that circ_CDR1as and its target gene GATA6 were significantly downregulated in PSCC, and their reduction in tumor samples was validated by an external dataset and qRT-PCR, indicating a potential regulatory relationship between them." (PMID 40657383, 2025). "Targeting GATA6 or TET1 disrupted CAF identity, impaired tumor growth, and attenuated stromal-tumor crosstalk in vitro and in vivo." (PMID 40216762, 2025). "Our data revealed that CAFs with reduced GATA6/TET1 exhibited decreased secretion of IL-6, VEGF, and TGF-β (p < 0.05 vs. Control 1), critical mediators of angiogenesis and tumor-stroma crosstalk." (PMID 40216762, 2025). "The low expression of GATA6 and high expression of the KRT81 genes in patient PDCA14 suggest that this tumor is squamous-like and therefore, a more aggressive subtype." (PMID 38968363, 2024). "GATA6+ LPM invade liver metastases directly from the peritoneum and contribute to metastatic tumor growth and recurrence." (PMID 39192982, 2024). "Some TFs were specific for individual cell lines, others were shared between two cell lines, and a total of eight TFs were shared amongst all three tumor types, including TEAD1, TEAD2, TEAD3, TEAD4, GRHL2, RUNX2, AP1, and GATA6." (PMID 38912065, 2024). "GATA4 and GATA6 expression was studied by IHC in TMA samples of normal tissue, PanIN, tumor tissue and lymph node metastases from a series of 89 patients with resected PDAC." (PMID 36830789, 2023). "The results obtained in our study suggest that the tumor expression of the transcription factors GATA4 and GATA6, measured by IHC techniques, is modified throughout tumor development." (PMID 36830789, 2023). "The capacity of Hpa2 to regulate the expression of key regulators of acinar cell differentiation such as PTF1, GATA6, and MIST1 grant further support for the critical role of Hpa2 in the exocrine pancreas and its tumor suppressor characteristics." (PMID 37491420, 2023). "GATA6-KO mice exhibit extensive ADM and accumulation of adipocytes and, in the context of an active KRas (KRas*;Gata6-/- mice), accelerated tumor development." (PMID 37491420, 2023). "PACpAInt-Comp was able to discriminate between GATA6 + /Claudin18+ versus KRT17+ areas, with AUCs of 0.87 and 0.75 for basal-like and classical tumor scores, respectively." (PMID 37311751, 2023). "Collectively, this study identifies the tumor suppressive activity of LINC00261 in PC, showing that this lncRNA limits the functions of PC stem through an ITIH5/GATA6 regulatory pathway." (PMID 34446696, 2021).
tumor (continued). "In line with this hypothesis, a high frequency of classical PDAC in the pancreas head has been observed regardless of the tumor (clinical) stage, associated with high GATA6 transcript levels (typically detected in classical PDAC) in the benign pancreatic tissue adjacent to the tumor." (PMID 34503261, 2021). "The zinc-finger transcription factor, GATA binding protein 6 (GATA6), displays a key role in enhancing or suppressing tumor progression, with the role played depending on the tumor origins." (PMID 34446696, 2021). "The classical subtype expressed GATA6 (the endodermal lineage-specifying transcription factor) and exhibited KRAS dependency while QM-PDA subtype correlated with high tumour grade and poor prognoses." (PMID 33248227, 2021). "Hypomethylation-mediated GATA6 activation induced aberrant CD137 ligand expression and promoted multiple tumor-driving pathways in the proliferation of CTCL cell lines and tumor formation in NSG and C57BL/6 mouse models." (PMID 33628583, 2021). "Binding of GATA6 to the DKK1 promoter lead to a down-regulation of DKK1 and thus to a consecutive activation of the Wnt pathways and tumor progression." (PMID 32075129, 2020). "In summary, our study identifies novel epigenomic mechanisms by which GATA6 modulates LUAD proliferation, differentiation, and the activation of lineage-specific tumor suppressive pathways." (PMID 32157212, 2020). "As such, in KP tumor cells grown as organoids, BMP activation functions as a cytostatic signal, and this pathway can be constrained by GATA6." (PMID 32157212, 2020). "Furthermore, GATA6 was expressed at comparable levels in primary tumours (n=145) and adjacent normal pancreas (n=46) included in a recently published dataset, while it was significantly reduced in metastases (n=61) (p<0.001), consistent with an antimetastatic role for GATA6 in patients." (PMID 27325420, 2017). "To solve this conundrum, we reanalysed GATA6 gene copy number changes in three PDAC series (CNV):32, 33, 34 13/117 (11%) tumours showed amplifications, but losses occurred at a similar rate (17/117, 14.5%)." (PMID 27325420, 2017). "We analysed GATA6, E-cadherin and FOXA2 by IHC in tumours (n=25) using 4 mm core tissue microarrays (TMA), allowing for detection of intratumour heterogeneity." (PMID 27325420, 2017). "Unexpectedly, we found increased Gata6 gene expression and high levels of the active histone modification H3K4me3 on the Gata6 promoter in ADM and tumor cells." (PMID 26716510, 2016). "Gata6 expression gradually decreased as a function of age in SpC-c-MYC single transgenic and compound mice in primary tumor and liver metastasis." (PMID 19551151, 2009). "In mice lacking Gata6 gene expression, there was an increase in acinar to ductal metaplasia (ADM) and faster tumor growth driven by KRAS-G12V mutation." (PMID 40699746, 2025). "For example, knocking down FOXM1 or STAT3 in proximal models may reduce tumor growth, while overexpressing CDX2 or GATA6 could induce a more differentiated, less aggressive phenotype, advancing therapeutic understanding and precision medicine." (PMID 40862793, 2025). "SMAD4 transcriptionally upregulates GATA6, which amplifies TGF-β signaling by directly activating the TGF-β promoter, establishing a self-reinforcing feedforward loop critical for CAF identity and stromal-tumor crosstalk." (PMID 40216762, 2025). "Specific genes downregulated in HG tumours which showed significantly higher promoter methylation included the developmental transcription factors CDX1, CDX2, GATA6, HNF1A, the marker of colonic differentiation, DPP4, and the markers of LGR5+ intestinal stem cells, ASCL2, LGR5." (PMID 40473896, 2025). "The absence of GATA6 led to changes in tumor characteristics and a shift towards a basal phenotype, which was associated with patient outcomes and decreased responses to adjuvant chemotherapy, like 5 fluorouracil/leucovorin." (PMID 40699746, 2025).
tumor (continued). "The regulators in C1 LYZ+ tumor cells were mainly FOXA2, PDX1, GATA6, and PPARG." (PMID 40230840, 2025). "Our clinical and mechanistic data has established that UTX is a tumor suppressor in PDA and GATA6-UTX axis may serve as a potential target for PDA therapy." (PMID 37692474, 2024). "‐LPMs characterized in tumor‐bearing mice as F4/80high GATA6+ cells that proliferated during tumor progression.‐No expression of prototypical protumoral genes (IL10, TGFB and Retnla), but of proinflammatory genes (IL6, TNFA and IL1B)." (PMID 36658699, 2023). "We found that tumor expression of both GATA4 and GATA6 were significantly related to DFS." (PMID 36830789, 2023). "In contrast, survival in patients treated with adjuvant gemcitabine was independent of tumor expression of GATA6." (PMID 36830789, 2023). "Consistently with AMH, reduced GATA-6 expression correlated with larger tumor size, but not with prognosis." (PMID 36869369, 2023). "For example, miR-196b-5p was reported to enhance cell migration, proliferation, and tumor growth by affecting the tumor suppressors, TSPAN12, and GATA6 while increased miR-196b-5p expression in NSCLC was partly monitored by hypomethylation of its promoter section." (PMID 35514980, 2022). "Moreover, a study has revealed that GATA6 is essential in inhibiting EMT and tumor growth and is considered as a crucial biomarker in the progression of PC." (PMID 34446696, 2021). "In the regulatory network, several hub genes with maximum intramodular connectivity were identified (i.e., GATA6, SOX17, MEF2C, and SRF), which might propose novel insights for tumor angiogenesis." (PMID 34869004, 2021). "The results indicated that the expression of GATA1, GATA4 and GATA6 remarkably varied across the tumor stages, whereas GATA2, GATA3 and GATA5 demonstrated no significantly changes in different tumor stages." (PMID 34093794, 2021). "Our results demonstrated that overall mRNA levels of GATA6 were significantly decreased in the tumor samples in comparison with the non-cancerous tissues (median fold change (FC) = 0.3143; P = 0.0003)." (PMID 32704077, 2020). "Expression levels of GATA6 mRNA were significantly decreased in tumor samples relative to the corresponding non-tumor samples." (PMID 32704077, 2020). "Additionally, RT-PCR also indicated the gene expression of iPSC-derived tumor tissue in three germ layers, demonstrating expressions of GATA4 in endoderm; HAND1 and GATA6 in mesoderm; and TUBB3, MAP2, and GFAP in ectoderm." (PMID 33224204, 2020). "Interestingly, a significant inverse correlation was observed between MRP4 and GATA6 expression levels (p < 0.05), which has been recently described to inhibit EMT and tumor dissemination in pancreatic cancer." (PMID 32848164, 2020). "In addition, GATA6 knockdown in DMBA-treated K14ΔNLef1 mice led to an increased rate of tumour formation and increased the number of tumours per mouse." (PMID 33082341, 2020). "The qRT-PCR analysis showed that overall mRNA levels of GATA6 were significantly decreased in the tumor samples relative to the adjacent non-cancerous tissues (median FC = 0.3143; P = 0.0003)." (PMID 32704077, 2020). "We found that overall mRNA levels of GATA6 were significantly decreased in the tumor samples in comparison with non-cancerous gastric tissue (P = 0.0003)." (PMID 32704077, 2020). "Furthermore, we found while individual knockdown of either REG4 or LGR5 partially inhibited tumor cell growth in nude mice, the double REG4/LGR5 knockdown inhibited tumor growth to an extent similar to the GATA6 knockdown." (PMID 26387746, 2015). "Deletion of intestinal Gata4 and Gata6 results in an altered proliferation/differentiation phenotype, and an up-regulation of SAM pointed domain containing ETS transcription factor (Spdef), a transcription factor recently shown to act as a tumor suppressor." (PMID 24472151, 2014).
tumor (continued). "On the contrary, our results suggest that GATA-6 expression is stronger in the parts of the carcinoma nearest the surrounding stroma, i.e., in areas representing the invasive edge of the tumor (data not shown)." (PMID 18405344, 2008). "We also validated GATA6 amplification in B291 by quantitative (Q)-PCR, and by fluorescence in situ hybridization (FISH) in the parent tumor from which the B291 xenograft was derived, the latter excluding the possibility of amplification arising during xenograft growth." (PMID 18535672, 2008). "Analysis of GATA6 expression alone does not capture the complexity of tumor heterogeneity." (PMID 38733987, 2024). "As the dysregulation of immunoproteasomes and chemokines promotes immune evasion of cancer cells, suppression of MAF, GATA6, and DAB2 may contribute to the maintenance of the tumor microenvironment, which is advantageous for EMT and immune escape in the early stages of tumorigenesis." (PMID 37779141, 2023). "Importantly, similarly to what was seen in EP300 knockouts, ETC-159 treatment only minimally slowed down the GATA6-knockout tumor growth without reaching statistical significance, confirming that downregulating GATA6 conferred resistance to PORCN inhibition." (PMID 35536676, 2022). "Some of these molecular alterations found in squamous PDAC, such as inhibition of pancreatic epithelial differentiation genes (HNF4A and GATA6) together with increased hypoxia, HIF1A, C-MYC and WNT, insulin, and PI3K-AKT signaling, promote a metabolic rewiring of tumor cells to glycolysis." (PMID 34503261, 2021). "Moreover, we found that FAK KD HepG2 and Huh-7 cells, but not macroH2A1 KD HepG2 and Huh-7 cells, displayed a simultaneous significant increase (p < 0.01) in the mRNA levels of cancer stemness suppressor genes GATA6, SMAD4, and BMP7, and of tumor-promoting genes KDR and SOX2." (PMID 33182805, 2020). "Consequently, although GATA6 expression is initially required for the proliferation of LUAD cells, reducing GATA6 at later stages of tumor progression in conjunction with other epigenetic alterations may activate invasive programs and metastatic dissemination." (PMID 32157212, 2020). "However, expression of GATA5 or GATA6 proteins in tumor or peritumor tissues was not correlated with pivotal clinicopathologic factors." (PMID 24498120, 2014). "There was no significant relation between GATA6 staining and tumor grade (P = 0.18, χ2 test)." (PMID 18535672, 2008). "Although initially it was considered that GATA6 could have an oncogenic role in PDAC because its amplification and over-expression contributed to cell proliferation and cell cycle progression, more recently, a tumor-suppressive role in PDAC mouse models has been proposed." (PMID 36830789, 2023). "Besides, the correlation between the miR-181c overexpression after -and possibly induced by- the MAP treatment and the absence of the tumor relapse, can be partially explained considering that among its putative targets figure genes regulating the cell cycle, like GATA6, MAP2K1, PPM1A and Notch2." (PMID 26062442, 2015). "We therefore hypothesized that GATA6 contributes to pancreatic carcinogenesis in part through its effects on Wnt signaling, a putative relationship that has not been explored in any detail for this tumor type." (PMID 21811562, 2011). "However, it should be noted that it has been reported that in mice, nicotine promotes pancreatic carcinogenesis and tumor development via the down-regulation of GATA6, so it cannot be ruled out that GATA4 suppression may also be involved in tobacco induced carcinogenesis." (PMID 36830789, 2023). "Overall, these data demonstrate that GLPMs are recruited to tumor sites in CT26 but not MC38 liver metastases and subsequently downregulate their GATA6 transcription factor." (PMID 35906202, 2022).
tumor (continued). "However, quantitative analysis of GATA6 and VIM expression in mouse tissue was deemed unfeasible due to the widespread expression of GATA6 in both non-malignant epithelial and tumor cells, and the intense stromal labelling of VIM." (PMID 41006303, 2025).
cancer (105 papers, 2008 to 2026). A tumor composed of atypical neoplastic, often pleomorphic cells that invade other tissues. "Although GATA4, GATA5 and GATA6 are known to be associated with endoderm differentiation, recent studies over few years have demystified their role in cancer progression." (PMID 41514651, 2025). "GATA6 RNA and tissue (IHC) expression levels were correlated with each other and associated with the cancer stage." (PMID 40075743, 2025). "In contrast, genes such as APC, KRAS, CTNNB1, and GATA6, showed a higher mutation frequency in precancerous lesions than in advanced cancer." (PMID 39554798, 2024). "Loss of p300 led to loss of GATA6 expression, dedifferentiation of the cancers, and a molecular subtype switch." (PMID 35536676, 2022). "EP300 mutation and loss of GATA6 function bypassed the antidifferentiation activity of Wnt signaling, rendering these cancer cells resistant to Wnt inhibition." (PMID 35536676, 2022). "PLAU is associated with cell invasion in cancer through activation by GATA6, and is strongly upregulated in multiple malignancies including CRC31." (PMID 29453410, 2018). "GATA6 emerges as a new addition to the expanding repertoire of cancer-associated genes that hold pivotal roles in regular human development yet assume pathogenic functions in cancer due to deviant expression patterns." (PMID 39717718, 2025). "Furthermore, reactivation or silencing of the Gata6 locus has been associated with certain types of cancer affecting endodermal organs." (PMID 26498761, 2015). "There have also been reports of interactions between miR-944 and GATA6 in different kinds of cancers." (PMID 40657383, 2025). "Conversely, media from GATA6/TET1-overexpressing fibroblasts enhanced cancer cell aggressiveness, compared to fibroblasts transfected with the FLuc control template (Control 2) (p < 0.01)." (PMID 40216762, 2025). "We further evaluated the prognostic value of mKRAS ctDNA and GATA6 according to treatment modality owing to the heterogeneity of cancer stages among patients." (PMID 40075743, 2025). "For instance, GATA4 and GATA6 exert opposing effects in different cancers, which are influenced by chromatin remodeling and differential co-factor binding." (PMID 41514651, 2025). "ALDOB is transcriptionally induced by GATA6 and promotes fructose metabolism, which provides metastasizing cancer cells with the energy and materials necessary for increased growth." (PMID 38200154, 2024). "Aberrant expression of GATA4 and GATA6 contributes to cancer development, including GC, due to their critical role in physiological developmental processes." (PMID 39456519, 2024). "This controversial function of master regulators like GATA4 and GATA6 in cancer, alongside their crucial functions in maintaining normal tissue balance, complicates efforts for their direct utilization in diagnosis or treatment." (PMID 39456519, 2024). "These phenotypic findings manifest redox adjustments, collectively supporting the notion that downregulation of GATA6 in cancer cells provides resistance to oxidative stress through redox regulation." (PMID 39456519, 2024). "Specifically, we performed multiplex immunohistochemistry (mpIHC) analysis of GATA6 and cytokeratin 19 (a cancer cell marker) in matched primary tumours and metastases in liver tissues." (PMID 37914932, 2023). "To validate the RNA-seq analysis, we selected seven representative genes on the basis of their relevance for HGSOC (PAX8, EGFR) and other cancers (GATA6, RBM47, KHDRBS3), or for their involvement in the DDR pathway (ATRIP, POLH)." (PMID 37202753, 2023). "These cancers fall into the 2 main subtypes as before, with clear differential expression of the lineage factors GATA6 and HNF4A." (PMID 35536676, 2022). "We find that cells derived from this cancer fall into two classes regarding their sensitivity towards cisplatin, and we observe that cells with high expression levels of GATA6 and microRNA 200 are mostly sensitive." (PMID 34944784, 2021).